MTOR (mechanistic target of rapamycin kinase)
Diseases named in the same sentence as MTOR in open-access papers (continued):
Sharing a sentence is not in itself a finding about the gene and the disease.
cancer (continued). "The CXC-chemokine receptor-4 (CXCR4) pathway plays a role in cancer cell homing and metastasis, representing a potential target for cancer therapy, i.e., CXCR4 activates mTOR and the Bruton tyrosine kinase." (PMID 39411551, 2024). "In preclinical models and in vitro studies, honokiol has demonstrated its ability to induce apoptosis in cancer cells through multiple signaling pathways, including NF-κB, STAT3, EGFR, and mTOR." (PMID 39199550, 2024). "In malignant tumors, USP18 is elevated and activates AKT/mTOR signaling, promotes phosphorylated AKT (p-AKT) and p-mTOR protein expression, leading to cancer cell proliferation and migration." (PMID 39185411, 2024). "We identified recognized cancer driver genes (EGFR, MTOR, CCND1, and MYC) within Epi_C1_SPARC and Epi_C6_TCIM subclusters, observing high variability of CNVs in cell proliferation-related genes (TOP2A, MKI67)." (PMID 38720887, 2024). "Metformin also modulates the insulin/IGF-1 signaling pathway, which is frequently overactive in cancer cells, lowering insulin and IGF-1 levels and thereby reducing PI3K/AKT/mTOR pathway activation, which decreases cell growth and induces apoptosis." (PMID 39272875, 2024). "The genesis and progression of several illnesses, including cancer, as well as normal physiological functions, are significantly influenced by the PI3K/AKT/mTOR signaling pathway." (PMID 38168914, 2024). "Previous data in cancer cells indicated that PA synthesis by AGPAT‐2 (also known as LPPAT‐β) constitutes a mechanistic link between OA and mTOR activation." (PMID 38223199, 2024). "GSTP1 is the most studied GST isoform in different types of cancer, which has the potential to regulate AMPK/mTOR and MAPK signaling and facilitate protein synthesis and cell proliferation, respectively." (PMID 39044272, 2024). "MSCs can prevent cancer progression by inhibiting several signaling pathways, such as wnt/β-catenin and PI3K/AKT/mTOR." (PMID 39494266, 2024). "Standard cancer therapies often fail due to the generation of CSCs, with signaling pathways like Wnt, Hedgehog, Notch, hypoxia and PI3K/AKT/mTOR being aberrantly regulated in these cells." (PMID 38398072, 2024). "Dock7, together with mTOR, AKT and S6K, promotes signaling activities essential for cancer cell survival." (PMID 36711811, 2024). "Molecular studies have further shown that CBD affects multiple signalling pathways in cancer progression and cell proliferation, including the PI3K/AKT/mTOR pathway, the MAPK/ERK pathway, and the NF-κB pathway." (PMID 38891847, 2024). "Inhibiting the PI3K/AKT/mTOR pathway in EC cell lines HEC-1A and Ishikawa led to increased autophagy activity and reduced cancer cell proliferation, migration, and invasion, achieved by inhibiting FAM83B, a Family 83 member with similar sequences." (PMID 38601753, 2024). "Recently, mTOR inhibitors have been approved by the FDA for the treatment of advanced renal, breast and several other cancers." (PMID 38126764, 2024). "In gastrointestinal cancer, flavonoids influence cancer via pathways such as Wnt/β-catenin, PI3K/AKT/mTOR, AMP-activated protein kinase (AMPK), mitogen-activated protein kinase (MAPK), and nuclear factor-kappa B (NF-kB)." (PMID 38361124, 2024). "BMS-754807 suppresses PI3K/AKT/mTOR downstream of IR/IGF-1R, thus sensitizing cancer cells to CP and potentially increasing autophagic flux through suppression of mTOR." (PMID 38786030, 2024). "RNA-seq analysis provided further mechanistic insights and revealed that co-administration of RC48 and CM downregulated multiple cancer-related pathways, including the AKT/mTOR pathway, cell cycle, and cell proliferation." (PMID 38403634, 2024). "EGFR plays an important role in signalling pathways critical to cancer progression, including Ras/Raf/MEK/ERK and PI3K/AKT/mTOR." (PMID 39518152, 2024). "As a summary, our study demonstrated that cancer‐derived exosomal GKN1 inhibited proliferation, invasion, while inhibiting the PI3K/AKT/mTOR signaling pathway." (PMID 39524138, 2024).
cancer (continued). "Our prior work utilizing single cell evaluation of cancer cells exposed to FSS demonstrated that the levels of p-AKT and p-mTOR activation varies at the single cell level." (PMID 39000231, 2024). "One of the most significant oncogenic pathways in human cancer is the phosphatidylinositol-3-kinase (PI3K)/Akt and the mammalian target of rapamycin (mTOR) signaling pathways." (PMID 38338373, 2024). "Our results indicate that ANXA2 activates the Akt/mTOR signaling pathway and EMT in ESCC, thereby enhancing cancer invasion and metastasis through the regulation of β-catenin, Snail, and Claudin-1 proteins." (PMID 38658569, 2024). "A case of previous study has found that mTOR is correlated with GPX4 expression and the interaction between the two can regulate autophagy-dependent cancer cell death." (PMID 38526702, 2024). "The PI3K/AKT/mTOR signaling pathway is activated by EGFR and has a role in cancer cell growth and resistance in CCA to chemotherapy." (PMID 38339363, 2024). "In the complex orchestration of cancer progression, the crosstalk between the PI3K/AKT/mTOR pathway and other signaling cascades emerges as a captivating saga, intricately weaving the narrative of tumor tropism." (PMID 39369580, 2024). "The DEGs down-regulated in IFNAR1 KO MDBK cells infected with BVDV were mainly involved in cancer, Hippo, TGF-β, and mTOR pathways." (PMID 39100665, 2024). "SLC7A5 is highly expressed in many cancer types and has been shown to be oncogenic, largely due to its ability to import leucine, which promotes cell growth by activating the AKT/mTOR pathway." (PMID 38281999, 2024). "Another study highlighted the potential of TQ to inhibit PI3K/Akt/mTOR and JAK/STAT pathways in cancer cells." (PMID 39769174, 2024). "MiR-130a-3p modulated the metastatic spreading of the carcinoma via Suv39H1/AKT/mTOR axis and sponging of the non-coding RNA by HOTAIR upregulated Suv39H1 responses, promoting cancer cell growth and metastasis." (PMID 40176927, 2024). "The identification of oncogenic mutations that result in activation of the well-known PI3K/AKT/mTOR and RAS/MAPK pathways has enabled exploration of drug-based therapeutic interventions using small-molecule inhibitors that were developed for cancer treatment." (PMID 38488007, 2024). "Moreover, their proteomic analysis revealed activation of cancer-associated pathways involved in cell transformation and cancer progression, including PI3K/Akt/mTOR pathway; as a proof of concept, we could also demonstrate a role for this pathway in MM cell fitness." (PMID 38191367, 2024). "The stemness characteristics of cancer cells are maintained through various signaling pathways including Wnt/β-catenin, IL-6/STAT3, TGF-β, Notch, HH, Hippo, BMI1, NF-κB, PI3K/Akt/mTOR, and Ras/Raf/MAPK." (PMID 39273339, 2024). "To date, targeting PI3K/AKT/mTOR in HCC has yielded only partially positive results, mainly due to early onset drug resistance and cancer progression." (PMID 38473265, 2024). "After describing the direct mechanisms of the AKT pathway on cancer cells, it is important to discuss other indirect mechanisms that begin with AKT activation, such as the activation of the mTOR pathway." (PMID 39684551, 2024). "GOLPH3 is believed to promote cancer cell growth, inhibit cell death, and enhance migration through the regulation of signaling pathways like AKT/mTOR." (PMID 38828452, 2024).
cancer (continued). "Studies showed that human epidermal growth factor receptor (HER), SHP-2, mammalian target of rapamycin (mTOR), and cyclin-dependent kinase 4/cyclin-dependent kinase 6 (CDK4/CDK6) inhibitors improved adagrasib efficacy in KRAS G12C-mutant cancers." (PMID 38397927, 2024). "Targeting of AKT or mTOR has been suggested to be less effective than PI3K inhibition at inducing rapid (< 24 h) apoptosis and cell death in cancer cells." (PMID 39092562, 2024). "Accumulating evidence indicates that autophagy plays a complex role in cancer and is partly regulated by the PI3K/Akt/mTOR pathway." (PMID 38672636, 2024). "It has been reported that FLOT2 participates in the development of several types of malignant tumors, which activates the PI3K/AKT/mTOR, PI3K/AKT/MAPK pathways and NF-κB signaling to promote cell proliferation, migration and invasion." (PMID 38285090, 2024). "The mTOR–SREBP1 axis provides crosstalk between oncogenic signaling and cancer metabolism, and co-inhibition of metabolism and oncogenic signaling pathways is a strategy to improve treatment efficacy." (PMID 37444561, 2023). "The activation of proliferative and survival signaling pathways within cancer cells, such as the PI3K/AKT/mTOR and MAPK/ERK pathways, can promote cell growth and impede apoptosis, contributing to drug resistance." (PMID 37958383, 2023). "Next, we examined the inhibitory effects of AKT/mTOR signaling pathway in the presence of vehicle, Idelalisib, SRPIN340, or Idelalisib/SRPIN340 combination in the same cancer cell lines." (PMID 37670888, 2023). "As a classic cancer pathway, PI3K/AKT/mTOR signaling has been reported to be involved in the progression of NSCLC." (PMID 38049814, 2023). "Mutations in mTORC1 are often hyperactivating in cancer, and mTOR inhibitors Rapalogs (rapamycin and its analogs) have been clinically approved by FDA for treating some cancers." (PMID 36959802, 2023). "The use of these is currently considered a fruitful strategy to combat cancer, being mainly divided according to selectivity into three generic classes: pan-PI3K inhibitors, selective isoform PI3K inhibitors, and dual PI3K/mTOR inhibitors." (PMID 37050317, 2023). "Moreover, the activation of signaling pathways involved in sustaining cancer proliferation, including EGFR, HER2, B-RAF, ERK, mTOR, AKT, and SRC, have been identified in association with ADPKD, accumulating evidence that polycystins may be involved in cancer development and progression." (PMID 37510333, 2023). "Activating mutations in these genes have been frequently identified in many types of cancer and have been shown to result in hyper-activation of the PI3K/AKT/mTOR signaling pathway." (PMID 37109059, 2023). "NDDs and cancer signal through common cellular pathways, including MAPK and PI3K/ PDK1/AKT/mTOR with phosphatase and tensin homolog (PTEN), critical in cell division and growth, thus proliferation and cell differentiation." (PMID 37124926, 2023). "Collectively, based on in vitro and in vivo studies, melatonin possesses promising anti-cancer properties via its ability to regulate multiple cell signaling pathways such as MAPK and PI3K/Akt/mTOR." (PMID 36649046, 2023). "The mTOR kinase is responsible for phosphorylating downstream proteins, such as AKT, which are recognized as significant in promoting cancer growth." (PMID 37658623, 2023). "On the other hand, in some types of cancer, p21 can be oncogenic, promoting tumor growth and survival, inhibiting cell apoptosis, activation of the PI3K/Akt/mTOR pathway, and induction of angiogenesis." (PMID 37189754, 2023). "One of the principal pathways leading to mTOR activation is PI3K/AKT, which plays an essential role in cancer progression." (PMID 37223676, 2023).
cancer (continued). "In fact, Antrodia salmonea (AS), a traditional Chinese medicinal fungus with anti-cancer proprieties, reduced the phosphorylation of AKT and mTOR in SW620 cells, inhibiting AKT/mTOR signaling cascades." (PMID 37373349, 2023). "EMT is strongly interconnected with autophagy because both play a vital role in the occurrence and development of cancer and are regulated by various same signaling pathways, such as PI3K/AKT/mTOR, Beclin‐1, and JAK/STAT signaling pathways." (PMID 35676831, 2023). "Deregulated of PI3K/AKT/mTOR and Raf/MEK/Erk signaling pathways were observed simultaneously in human cancer cells, and the subsequent excessive production of ROS has been reported to be associated with apoptosis and autophagy." (PMID 37304865, 2023). "For instance, during cancer cell generation, mitochondrial fission inhibits cancer proliferation and metastasis through inhibiting PI3K/Akt/mTOR and Ras/Raf/MEK/ERK signaling pathways." (PMID 38151790, 2023). "Understanding the role of mTOR downstream regulators, 4E-BP1 and S6K1 is important in treating cancer at later stages because of their active role in cellular proliferation, protein synthesis, tumour angiogenesis, and metastasis." (PMID 37513916, 2023). "Nutrient sensing via mTOR is essential for growth and survival; however, in the context of TME, this is yet another mechanism cancer and immune cells exploit to compete for nutrients." (PMID 37274280, 2023). "On the other hand, low SYNPO2 expression and mutation can activate signaling pathways such as the PI3K/AKT/mTOR and the LATS2/YAP/TAZ pathways, promoting cancer development." (PMID 37544991, 2023). "Once activated, mTOR affects the translation of oncogenic and angiogenic proteins (including HIF-1α), thus supporting cancer progression." (PMID 38273861, 2023). "Changes in cellular pathway proteins like PI3K/Akt/mTOR and MAPK/ERK, which are extensively dysregulated in malignant tumors, also support malignant cells’ ability to avoid apoptotic death and contribute to chemotherapy resistance." (PMID 35867269, 2023). "KEGG enrichment analysis indicated that the activated pathways included HIF, pathways in cancer, TNF, PI3K‐AKT, mTOR, TGF‐β, cell cycle, and MAPK signaling." (PMID 37085918, 2023). "PI3K/Akt/ mechanistic target of rapamycin (mTOR) and Ras/Raf/MEK/ERK signaling pathways are considered to be promising targets for cancer therapy." (PMID 36829235, 2023). "In oxidative stress-induced cancers, three pathways are frequently activated: the PI3K/AKT/mTOR pathway, the JAK/STAT3 signal transduction pathway, and the NF-κB/MAPK pathway." (PMID 37760015, 2023). "Most experimental data have revealed that it electively targets CSCs and acts together with chemotherapy to exert antitumor effects in different cancers mainly through AMPK activation and PI3K/AKT/mTOR inhibition." (PMID 37368179, 2023). "We showed that many cancer-promoting pathways, including tumor angiogenesis, MAPK, and PI3K/AKT/mTOR pathways, were inactivated after GLUT3 silencing." (PMID 37258572, 2023). "LXRs are NRs that have been shown to promote cancer cell death through the effect of their ligands in preclinical studies of various cancers, partly due to reduced activity of the PI3K/Akt/mTOR pathway." (PMID 37341140, 2023). "Analogously to the oncogenic potential of MAGEA3/A6 expression in tumors resulting in enhanced proliferation by limiting mTOR-dependent autophagy, a similar role of MAGED2 is conceivable, which is abundantly expressed in many types of cancers." (PMID 37686237, 2023). "The pharmacological inhibition of the PI3K/AKT/mTOR pathway significantly reduces MYC levels and demonstrates therapeutic efficacy in MYC-driven cancers." (PMID 37755397, 2023). "PTEN is frequently downregulated in cancer, resulting in activation of the PI3K/AKT/mTOR pathway and consequent enhanced cell growth and proliferation." (PMID 37665633, 2023).
cancer (continued). "The 10 most enriched pathways included biological processes involved in apoptotic pathways and protein insertion into membrane, and metabolic pathways involved in cancers, as well as some also crucial to osteoclasts, such as PI3K‐Akt and mTOR." (PMID 37614303, 2023). "The first pathway is mTOR/PI3K/Akt signaling, which is dysfunctional in many cancers and is related to cancer cell growth, cancer cell survival, cytoskeletal movement, and resistance to cancer therapy." (PMID 36593951, 2023). "Curcumin decreased the high glucose-induced survival of cancer cells upon doxorubicin and methotrexate treatment, suppressed glucose uptake, lactate production, expression of GLUT1/3, MCT1/4, HIF1α, mTOR, STAT3, and multidrug resistance protein MDR-1." (PMID 38001865, 2023). "The PI3K/Akt/mTOR (mechanistic target of rapamycin kinase) pathway is a downstream effector of KRAS activation and is also involved in glucose metabolism in cancer cells." (PMID 37345116, 2023). "Pathways in cancer, PI3K-AKT pathway, Ras pathway, apoptosis pathway, and mTOR pathway are important signaling pathways for the treatment of disease." (PMID 38065884, 2023). "MTOR is considered to be the most typical negative regulator of autophagy, PI3K/Akt/mTOR, and is usually activated in cancer cells." (PMID 37663256, 2023). "HER3 mediates resistance to EGFR, HER2, PI3K/AKT/mTOR directed therapies and endocrine therapy and its allosteric function is critical for HER2-amplified cancer growth." (PMID 36966267, 2023). "Histone deacetylation is crucial for the regulation of chromatin structure and maintenance of cancer cell state and activation of the PI3K/AKT/mTOR signaling cascade is a tumor growth–promoting pathway." (PMID 37823778, 2023). "Consistently, we observed that phosphorylation of the S6 ribosomal protein, a direct mTOR downstream target previously found to be involved in the regulation of DNA repair, at serines 240/244 also decreased in NCS-treated cancer cells." (PMID 37998381, 2023). "The process of ferroptosis involves signaling pathways that play a role in cancer biology, such as the AMP-activated protein kinase (AMPK)-RAS/MAPK and AMPK/mTOR/p70S6k pathways and the NRF2-KEAP1 pathway." (PMID 36677534, 2023). "Two other intracellular signaling pathways of prime importance in cancer proliferation are the phosphatidylinositol 3-kinase (PI3K)-Akt and the mammalian target of rapamycin (mTOR)." (PMID 37765192, 2023). "There is growing evidence that the AKT/mTOR pathway is involved in the regulation of critical processes like EMT, motility, and metastasis of cancer cells." (PMID 38023171, 2023). "Compared with paracancerous tissues, the mRNA expression of SFXN1 is significantly increased in cancer tissues, and SFXN1 promotes the progression of NSCLC by activating the mTOR signaling pathway." (PMID 36902385, 2023). "The drug panel used for response screening included 48 anti-cancer compounds of seven classes targeting angiogenesis (n = 3), the cell cycle (n = 8), DNA damage (n = 6), MAPK (n = 3), PI3K/AKT/mTOR (n = 3), protein tyrosine kinase (n = 7), and others (n = 18)." (PMID 36717865, 2023). "The KEGG analysis indicated a concentration of genes in multiple cancer-promoting pathways, including the PI3K-Akt signaling pathway, mTOR signaling pathway, and AMPK signaling pathway." (PMID 37688768, 2023). "In fact, the antidiabetic drug metformin has been investigated as an anti-cancer agent due to its ability to promote the activity of AMPK, suppress the action of mTOR, and subsequently attenuate SHH/GLI signaling." (PMID 37568705, 2023). "It influences the proliferation, survival and EMT of cancer cells through induction of ROS and regulation of PI3K/AKT/mTOR." (PMID 38023171, 2023).